IL4 (interleukin 4)
Diseases named in the same sentence as IL4 in open-access papers (continued):
Sharing a sentence is not in itself a finding about the gene and the disease.
autoimmune disease (continued). "Laboratory animal studies suggest that mercury compounds may induce autoimmune disease and increases in interleukin-4 (IL4) production and IgE levels in certain rodent strains." (PMID 20562055, 2010). "Surprisingly, IL-4 deficiency has not been associated with increased susceptibility to autoimmune diseases, suggesting a supportive role for IL-4 in suppression of inflammatory responses against self-Ags." (PMID 20090936, 2010). "Therefore, the balance between proinflammatory (IL-2, IFN-γ and TNF) and regulatory (IL-4, IL-10 and TGF-β) cytokines probably determines any predisposition to develop autoimmune disease." (PMID 16759382, 2006). "Systemic lupus erythematosus is an autoimmune disease, during the course of which the occurrence of hematological and other organ manifestations is a significant clinical problem, and a variety of cytokines, such as IL-4, IL-6, and interleukin 10 (IL-10), can have a significant impact on this." (PMID 38139169, 2023). "Hence, IL-4 could be considered as a potential tool for treating autoimmune diseases as evidenced by its protective effect in murine models of RA." (PMID 33488761, 2021). "Thus far, several previous studies have demonstrated that IL-4 may have a pro- or anti-inflammatory role in the development of organ-specific inflammation in classical autoimmune disease models." (PMID 32095039, 2019). "Indeed, studies have demonstrated that aberrant and continued IL-4 expression in vivo can rescue autoreactive B cells from apoptosis, enhance their survival, and induce activation of autoreactive B cells and thereby promote autoimmune diseases." (PMID 27651750, 2016). "Firstly, we detected IL-2, IL-4, IL-5, IL-13, IL-17A, IL-17F, IL-22, IFN-γ, and TNF-α in the plasma to exclude the influence of infection or autoimmune disorders, and the standard curves were verified." (PMID 38343544, 2024). "Interleukin-4 (IL4) and Interleukin-13 (IL13) are anti-inflammatory cytokines and are considered as important mediators in pathology of the autoimmune diseases." (PMID 37090926, 2023). "In Hashimoto thyreoiditis, another IgG-mediated autoimmune disorder, FcRn expression in thyroid epithelial cells was shown to be reduced, and interferon-γ (IFN-γ), tumor necrosis factor-α, and interleukin-4 or -10 treatment diminished FcRn expression." (PMID 35326398, 2022). "Among these markers, GATA3 and STAT5 play essential roles in generating IL‐4 during the process of Th2 polarization, and the production of IL‐4 can enhance Th2 polarization and augment GATA3 expression in autoimmune diseases." (PMID 32406154, 2020). "Animal studies have shown that IL-4 increased the survival of mice exposed to lethal doses of LPS4, and anti-inflammatory activity in several autoimmune diseases." (PMID 29257842, 2017). "Consistent with AA as a Th1-mediated autoimmune disease, mice with BMF displayed higher level of IFN-γ and lower level of IL-4." (PMID 25254224, 2014). "The ratio of IFN-γ+/IL-4+ CD4+ T cells represents the balance between pro-inflammatory Th1 and anti-inflammatory Th2 cells, and is regarded an important variable in autoimmune diseases." (PMID 21179201, 2010). "In contrast, Th2 cells produce IL-4, which constrains cell-mediated immunity (CMI) and possibly inhibits the onset of autoimmune disease." (PMID 16759382, 2006). "Contrary to findings in autoimmune disease and cancer, the blockade of LAG-3 increased the production of Th1-type tumor necrosis factor (TNF)-α and interferon (IFN)-γ, but decreased Th2-type and Treg-type IL-4, IL-10 and transforming growth factor (TGF)-β1." (PMID 41023624, 2025). "MS is an autoimmune disease induced by autoreactive T lymphocytes that is characterized by an imbalance of pro-inflammatory cytokines, such as TNF, interferon γ (IFN-γ), IL-2 and lymphotoxin, and regulatory cytokines (e.g., IL-4 and IL-10)." (PMID 40076462, 2025).
autoimmune disease (continued). "DN T-cells with T helper (Th)-like properties are capable of secreting cytokines such as interleukin (IL)-4, IL-17, interferon-γ (IFN-γ), and tumor necrosis factor (TNF)-α, thereby assuming a role analogous to that of CD4 Th cells in cases of infection and autoimmune disease." (PMID 39544989, 2024). "MS is an autoimmune disease induced by autoreactive T-lymphocytes that is characterized by an imbalance of pro-inflammatory cytokines, such as TNF-α, IFN-γ, IL-2 and lymphotoxin, and regulatory cytokines (e.g., IL-4 and IL-10)." (PMID 39596101, 2024). "Cells from donors without autoimmune disease, in response to exosomes produced by resting astrocytes, increased the number of IL-4-producing cells as compared to cells cultured without exosomes." (PMID 37108633, 2023). "Some studies of autoimmune diseases have reported that MSC-EVs drive a shift from Th1 toward Th2 cells and rebalances Th1/Th2 cells by downregulating proinflammatory cytokines TNFα and IFNγ and upregulating anti-inflammatory cytokines IL-10 or IL-4." (PMID 34447855, 2021). "It has been reported that α-GalCer stimulation can induce iNKT cells to produce both anti-inflammatory cytokines (e.g., IL4, IL13, and IL10) and pro-inflammatory cytokines (e.g., IFNγ, TNFα, and IL17), ultimately determining the outcome of autoimmune diseases such as EAE." (PMID 30766446, 2019). "One study identified that Golli-MBP (human Golli-myelin basic protein) was suspected to play a role in the etiology of autoimmune diseases and the gene expression ratio of IFN-γ/IL-4, and increased Golli-MBP was related to a lower ratio of IFN-γ/IL-4 in OLP patients." (PMID 31181785, 2019). "Upon activation, iNKT cells play a protective or detrimental role in infectious and autoimmune diseases and mediate tumor surveillance by rapidly secreting copious levels of cytokines such as interferon-γ (IFN-γ) and interleukin 4 (IL-4) and activating diverse immune cells." (PMID 30250136, 2018). "Single administration of OCH could prevent EAE, characterized by Th1-mediated autoimmune disease, via inducing Th2 bias of NKT cells to produce IL-4." (PMID 25254224, 2014). "Although Th2 cells and FoxP3+ Tregs have been reported to be critical for maintaining immune tolerance in autoimmune diseases, no significant increase of IL-4-producing or FoxP3 expression CD4+ cells was found in MOG35-55/I-Ab dimer-treated mice." (PMID 23077616, 2012). "However, because this glycolipid stimulates NKT cells and induces the production of both interleukin (IL)-4 and interferon (IFN)-γ, a search for glycolipids that selectively induce IL-4 production was initiated to treat Th1 cytokine–dependent autoimmune diseases such as MS." (PMID 38224478, 2024). "On further adjusted analyses, stratified by the level of expression of specific cytokines in autoimmune diseases, 30-day mortality was reduced in those autoimmune diseases with overexpression of IL-1, IL-6, IL-12, IFN-γ, and TNF-α, as well as in those with reduced expression of IL-4 and IL-10." (PMID 35271683, 2022). "Also, in certain mouse models, the IFN-γ/STAT1 pathway mediates protective effects in autoimmune disease and arthritis, and lack of IL-4 and STAT6 suppresses arthritis." (PMID 27942004, 2016). "Studies using models of experimental autoimmune diseases such as arthritis, diabetes, and experimental autoimmune encephalomyelitis (EAE) have indicated that activation of iNKT cells by OCH ameliorates or prevents these Th1-mediated diseases, attributed to induction of IL-4 and Th2 skewing." (PMID 25807531, 2015). "Therefore, in assessing patients with autoimmune disorders, the measurement of Th1 (IFN-γ), Th2 (IL-4, IL-5, IL-13) and Th17 (IL-17) cytokine production by cultured lymphocytes will guide CAM practitioners in tailoring proper treatments for Th1- and Th17-mediated autoimmune diseases." (PMID 19622600, 2011).
autoimmune disease (continued). "Since the range of immunologic effects of IL13 may not overlap completely with those of IL-4, it will be critical to determine the potential benefit provided by responses biased toward IL-13 production in the context of autoimmune disease." (PMID 21179412, 2010). "Flow cytometry analysis of the composition of T-cells producing IFN-γ (Th1), IL-17A (Th17), IL-4 (Th2), and IL-10 (Treg) revealed no visible changes in the percentage of Th1 and Treg cells in response to various exosomes for both MS patients and control subjects without autoimmune disease." (PMID 37108633, 2023). "Therefore, the treatment of autoimmune disease using IL-4 may not achieve the desired effect when used repeatedly." (PMID 33816637, 2021).
airway hyperresponsiveness (123 papers, 2004 to 2026). "We demonstrate that camel milk suppresses airway hyperresponsiveness, Th2 and Th17 cell recruitment, and associated cytokines (IL-4, IL-5, IL-13, IL-17A), while reducing dendritic cell activity and CCL17 expression in the lungs." (PMID 40577410, 2025). "Meanwhile, the function of interleukin-4 (IL-4) in Ch. pneumoniae respiratory infection and its association with the development of airway hyperresponsiveness (AHR) in adulthood and causing allergic airway disease (AAD) are not understood properly." (PMID 34226412, 2021). "As a result, Th2 cells increase in T-bet-deficient mice and spontaneously help to form airway hyperresponsiveness associated with overproduction of Th2 cytokines (IL-4, IL-5 and IL-13) and to cause infiltration of eosinophils and lymphocytes." (PMID 32489402, 2020). "It is worth mentioning here that the human small airways express IL4/13, which are in turn associated with airway hyperresponsiveness, and may at least in part explain our findings." (PMID 39941577, 2025). "The allergic form is an adaptive T helper 2-driven disease characterized by elevated levels of interleukin (IL)-5, interleukin-4 (IL-4), and IL-13, associated with enhanced levels of circulating and lung eosinophils, elevated serum IgE, mucus hypersecretion and airway hyperresponsiveness." (PMID 34744763, 2021). "IL-4, IL-5, IL-6, and IL-13 have been shown to maintain this cycle of allergic inflammation with IL-4 promoting Ig isotype switching, IL-5 inducing eosinophil differentiation and migration, and IL-13 causing goblet cell hyperplasia and airway hyperresponsiveness." (PMID 30380761, 2018). "Furthermore, in vitro and in vivo experiments clearly show that Δ12-PGJ3 differed from the synthetic agonist of DP1 receptor, ZK118182, in terms of its ability to induce airways hyperresponsiveness, release of histamine, and IL-4 expression, which are all associated with hypersensitivity." (PMID 24312486, 2013). "IL‐4 and IL‐13, which share the Type 2 receptor IL‐4R, play a crucial role in the pathogenesis of airway hyperresponsiveness, goblet cell metaplasia, and increased production of airway mucus in patients suffering from allergic asthma." (PMID 41568067, 2026). "IL-4 and IL-5 are key cytokines that promote eosinophilic inflammation and mast cell activation, and elevated levels of both contribute to airway hyperresponsiveness, exacerbating the progression of BA." (PMID 40951891, 2025). "In our investigation, the choice of indicators, including airway hyperresponsiveness, cytokine concentrations (IL-4, IL-5, and IL-13), IgE titers, and histopathological examinations, was pivotal for evaluating the efficacy of hydrogen therapy." (PMID 41146240, 2025). "In an animal study providing IL-12 to mice previously exposed to an antigen, airway hyperresponsiveness and pulmonary eosinophilia were eliminated, and the expression of IL-4 and IL-5 was diminished." (PMID 41155381, 2025). "Elevated levels of IL-4 and IL-13, for example, promote IgE production and the activation of mast cells, leading to airway hyperresponsiveness and remodelling." (PMID 40951891, 2025). "In SA, epithelial-derived cytokines play a central role in initiating and sustaining type 2 (T2) inflammation by activating the IL-4, IL-5, and IL-13 axis, leading to increased eosinophils, elevated serum IgE, and heightened airway hyperresponsiveness." (PMID 41169790, 2025). "At the molecular level, the HDM challenge elevated the expression of major Th2 cytokines (IL-4 and IL-13), IL-17a, and muc5ac, which are key mediators of airway hyperresponsiveness and mucus overproduction." (PMID 39682780, 2024). "I.n. challenge of sensitized animals led to increased BAL type 2 cytokines (IL-4, IL-5 and IL-13) as well as airway hyperresponsiveness." (PMID 39157265, 2024).
airway hyperresponsiveness (continued). "IL-4 also promotes the migration of Th2 cells and eosinophils to inflamed sites, induces goblet cell hyperplasia, and triggers airway hyperresponsiveness and mucus hypersecretion." (PMID 39684703, 2024). "When they gave anti-TSLP monoclonal antibody, the DEHP enhanced airway inflammation, Th2 cytokines (IL-4, IL-5 and IL-13) production, and airway hyperresponsiveness were reduced via neutralized TSLP." (PMID 37545493, 2023). "IL-4 plays a key role in Th2 cell differentiation, while IL-5 is specifically involved in eosinophilic inflammation and airway hyperresponsiveness." (PMID 36755351, 2023). "Resveratrol significantly attenuated the level of Th2 cytokines such as IL-4 and IL-5 in plasma and bronchoalveolar lavage fluid and also effectively suppressed airway hyperresponsiveness and mucus hypersecretion, in the asthmatic mouse model." (PMID 35796922, 2022). "Recently, we showed that the pre-treatment of adult mice with LPS before an allergic inflammation partially prevent CCSP and SP-D reduction in CC, with the increase of IL-4 levels, hindering airway hyperresponsiveness." (PMID 32379832, 2020). "It has been reported that MT inhibited ovalbumin (OVA)-induced airway hyperresponsiveness (AHR) in mice by decreasing the production of IL-4 and IL-13, and increasing the expression of interferon (IFN)-γ." (PMID 33041782, 2020). "Carbonic anhydrase II (CA2), which was negatively correlated with miR-26a-5p and significantly upregulated in exacerbated horses, is known to be upregulated by Th2 cytokines like IL-4 and IL-13, and reportedly promotes airway hyperresponsiveness." (PMID 32998415, 2020). "Th2 cytokines, such as IL-4, 5 and 13, are known as major players in development of airway hyperresponsiveness (AHR), eosinophil infiltration, and mucus hypersecretion." (PMID 30783201, 2019). "In the present study, T. IIA inhibited the infiltration of inflammatory cells in the lung, reduced the productions of IL-4, IL-5, and IL-13, and dampened airway hyperresponsiveness." (PMID 30834081, 2019). "IL-13, IL-1 β, IL-6, IL-4, IL-5 are Th2 cell-type factors, mainly involved in mucus secretion, eosinophil production, IgE synthesis, and airway hyperresponsiveness." (PMID 31024302, 2019). "IVE and AET ameliorated OVA-driven airway hyperresponsiveness (p < 0.01), pulmonary eosinophilic infiltration (p < 0.05), mucus hypersecretion (p < 0.01), and IL-4, IL-5, IL-13, and CCR3 production (p < 0.05), as well as IgE levels (p < 0.01)." (PMID 29062168, 2017). "AS-IV markedly suppressed airway hyperresponsiveness and reduced IL-4, IL-5, and IL-17 levels and increased INF-γ levels in the BALF." (PMID 29234390, 2017). "After the first challenge, antigen exposure induced a transient airway obstruction and airway hyperresponsiveness, high levels of IL-4 and IL-5 in lung and airway globet cells proliferation at the third antigenic challenge." (PMID 25977751, 2015). "In mice chronically exposed to ovalbumin, chronic administration of budesonide reduced airway hyperresponsiveness, as well as leukocyte infiltration, with a decrease in the production of Th2 mediators such as IL-4, IL-12, and eotaxin-1." (PMID 26264367, 2015). "Intratracheal administration of adenoviruses carrying PTEN cDNA can reduce the levels of interleukin-4 and −5 in bronchoalveolar lavage fluid, bronchial inflammation and airway hyperresponsiveness." (PMID 24940423, 2014). "The biomarkers include pulmonary histopathology, airway hyperresponsiveness (lung function), IgE, IL-4, IFN-γ and eosinophils." (PMID 22701742, 2012). "The second group is “moderately sensitive biomarkers”, including IL-4, recruitment of eosinophils and airway hyperresponsiveness (Re, Ri and Cldyn)." (PMID 22701742, 2012). "PIO and DEX demonstrated similar abilities to reduce airway hyperresponsiveness, pulmonary recruitment of inflammatory cells, serum IgE, and lung levels of IL-4, IL-5, TNF-α, TGF-β, RANTES, eotaxin, MIP3-α, Gob-5, and Muc5-ac." (PMID 18053220, 2007).